IL5RA (interleukin 5 receptor subunit alpha)
Diseases named in the same sentence as IL5RA in open-access papers (continued):
Sharing a sentence is not in itself a finding about the gene and the disease.
nematode infection (1 paper, 2018). "The role of PPARG, DUOX2 and IL5RA genes in relation to the immune response has been previously reported in different nematode infection studies." (PMID 29703268, 2018).
pancreatic cancer (1 paper, 2020). "IL-5 stimulated tumor cell migration and activation through STAT5 signaling, thereby suggesting an unreported tumor-promoting role for IL-5Rα in pancreatic cancer." (PMID 32552827, 2020).
pancreatic tumor (1 paper, 2020). "Collectively, IL-5/IL-5Rα signaling in the mouse and human pancreatic tumors microenvironment is a novel mechanism to facilitate tumor progression." (PMID 32552827, 2020). "Results suggest that IL-5 in the pancreatic compartment stimulates increased IL-5Rα on ductal tumor cells to increase pancreatic tumor motility." (PMID 32552827, 2020). "Results suggest that pancreas localized IL-5 stimulates the increase of IL-5Rα on ductal tumor cells and increases pancreatic tumor motility." (PMID 32552827, 2020). "Collectively, IL-5/IL-5Rα signaling in the pancreatic tumor microenvironment is a novel mechanism to facilitate tumor progression." (PMID 32552827, 2020). "Also, tumorigenic human L3.6pl and murine Panc02 pancreatic tumor cells retained expression of IL-5Rα when orthotopically injected into NSG mice or C57Bl6 mice, respectively." (PMID 32552827, 2020). "Findings led to the discovery of a new signaling mechanism of crosstalk between IL-5 expression in the pancreatic microenvironment and IL-5Rα on pancreatic tumor cells, which may be a novel targetable pathway in pancreatic tumor progression." (PMID 32552827, 2020). "More studies are needed to delineate the regulation of IL5Rα and STAT5-activation- mediated induction of migration in pancreatic tumor cells." (PMID 32552827, 2020).
plasma cell tumors (1 paper, 2023). "In summary, these suggest that IL5RA may be involved in the progression of plasma cell tumors." (PMID 37236993, 2023).
sensitization (1 paper, 2014). "SNPs in or near JAK2, CNOT6, MAML1, CD40, IL-4R, and IL-5RA genes were associated with allergic sensitization and SNPs in or near JAK1, JAK3, IL5RA, FCER1A, and ADAM33 genes were associated with cockroach sensitization." (PMID 25505553, 2014).
Shock (1 paper, 2019). The state in which profound and widespread reduction of effective tissue perfusion leads first to reversible, and then if prolonged, to irreversible cellular injury. "Neutrophils isolated from the lungs in a mouse model of resuscitated hemorrhagic shock and tissue trauma have also been shown to express IL-5Rα expression." (PMID 31415658, 2019).
trypanosomiasis (1 paper, 2021). Infection with protozoa of the genus trypanosoma. "Additional genes highlighted in our study were CFH, TRNT1, IL5RA, MGAT4C and NTS, which could be also relevant for the trypanosomiasis resistance in cattle." (PMID 34351956, 2021).
tuberculosis (1 paper, 2020). A chronic, recurrent infection caused by the bacterium Mycobacterium tuberculosis. "Recently IL5RA was found to be under-expressed in human tuberculosis (TB) patients compared with healthy controls." (PMID 32033399, 2020).
uveal melanoma (1 paper, 2022). A melanoma derived from melanocytes of the uveal tract. "RT-qPCR results displayed remarkably higher expression of IL5RA in uveal melanoma tissues than in normal uveal tissues." (PMID 35468881, 2022). "Among them, IL5RA was considerably upregulated in uveal melanoma, exhibiting the largest fold change." (PMID 35468881, 2022).
tumor (13 papers, 2009 to 2026). "Upregulation of JMJD2C markedly increased the volume and weight of MUM-2B cell-derived tumors, while loss of IL5RA contributed to marked decreases in tumor volume and weight in the presence of JMJD2C." (PMID 35468881, 2022). "The second group, whose expression peaked at the early-MM disease stage, consisted of Il5ra, a cytokine receptor, Mgmt, a methyltransferase crucial for genome stability, and Tsc22d1, a pro-apoptotic tumour suppressor." (PMID 34732728, 2021). "Although the IL(R)-based signature exhibited powerful predictive ability, these signature members themselves (IL-7R, IL-5RA, IL-20RB, IL-11, and IL-22RA1) were rarely reported to be used to predict tumor prognosis." (PMID 34497605, 2021). "Expression of CCL18, IL-5RA, and HLA-B as well as macrophage tumor infiltration could identify patients who can potentially benefit from treatment with immune checkpoint inhibitors." (PMID 38790160, 2024). "At the cellular level, USP18, TLR7, IL21R, GCNT1 and CHST7 were expressed in various tumor cell lines, while the expression of LHX2, IL2RA and IL5RA was low in CCLE." (PMID 34001679, 2021). "RFX1 downregulates such pro-tumor factors like Toll-like receptor 4 (TLR4), Interleukin 17A (IL17A), interleukin 5 receptor subunit alpha (IL5RA), and helps in cancer mitigation while being anti-inflammatory." (PMID 33964962, 2021). "To determine endogenous expression of IL-5Rα we analyzed tissues from our genetically modified mouse models and PDAC tumor cells lines." (PMID 32552827, 2020). "Using an eosinophil gene signature (SIGLEC8, RNASE2, RNASE3, IL5RA, and CCR3), it was found that eosinophil infiltration inside the tumor correlates with increased CD8+ T cell and IFN-γ signatures and was shown that tumor eosinophils enhance CD8+ T cell activation, leading to tumor eradication." (PMID 39496729, 2024).
inflammation (5 papers, 2018 to 2025). Aberrant reaction of the microcirculation characterized by movement of fluid and leukocytes from the blood into extravascular tissues. "The nasal tissue of NERD patients has been demonstrated to have a high expression of IL-5Rα, supporting the biological activity of IL-5 beyond eosinophils and severe sinonasal inflammation." (PMID 39404884, 2025). "IL4 and IL5RA are well-characterized cytokines responsible for Th2 cell differentiation and effector function, ADAM19 is involved in airway and vasculature remodeling, and PRG2 and EPX are both eosinophil-related proteins that play key roles in eosinophil-related airway inflammation." (PMID 29692868, 2018).
Respiratory Disease (4 papers, 2020 to 2024). "We found exclusive expression of IL5RA in NP ASCs compared with tonsils, in line with a similar report on IL5RA overexpression in aspirin-exacerbated respiratory disease B cells." (PMID 39253973, 2024). "In this sense, it has been described that IL5RA expression is increased in patients with NP, particularly those with Aspirin-Exacerbated Respiratory Disease." (PMID 33644088, 2020).
cancer (3 papers, 2021 to 2023). A tumor composed of atypical neoplastic, often pleomorphic cells that invade other tissues. "The enrichment analysis of DEGs related to IL5RA showed enrichment in cancer-related pathways." (PMID 37236993, 2023).
IL5RA also shares sentences with these, for which no sentence is quoted: hypereosinophilic syndrome (6 papers); infection (5); allergic rhinitis (3); Allergy (3); eosinophilic granulomatosis with polyangiitis (3); chronic rhinosinusitis (2); respiratory infections (2); allergic conjunctivitis (1); allergic respiratory disease (1); alveolar rhabdomyosarcoma (1); arrythmia (1); Autoimmunity (1); breast carcinoma (1); bullous pemphigoid (1); cholangiocarcinoma (1); chronic lung disease (1); chronic lymphocytic leukemia (1); chronic obstructive pulmonary disease (1); chronic pancreatitis (1); Chronic Spontaneous Urticaria (1); colorectal cancer (1); congestive heart failure (1); Down syndrome (1); eosinophilic leukemia (1); food allergies (1); helminth infections (1); influenza (1); juvenile arthritis (1); leukemia (1); lung carcinoma (1).
A further 30 diseases each share a sentence with IL5RA in 1 paper.